INS (insulin)
Diseases named in the same sentence as INS in open-access papers (continued):
Sharing a sentence is not in itself a finding about the gene and the disease.
Glucose intolerance (continued). "Glucose intolerance was intrinsic to beta cells as βp65KO islets failed to secrete insulin ex vivo in response to a glucose challenge and were unable to restore metabolic control when transplanted into secondary chemical-induced hyperglycaemic recipients." (PMID 37311878, 2023). "Three weeks of clopidogrel treatment of young‐adult male mice resulted in glucose intolerance and diminished insulin secretion upon glucose stimulation but did not affect insulin sensitivity (and EV5A)." (PMID 37490001, 2023). "We found that mice exposed to air pollution particles via gavage developed glucose intolerance and—despite elevated glucose levels—they were not able to mount a compensatory increase in insulin secretion, consistent with beta-cell dysfunction." (PMID 36895000, 2023). "The significantly increased blood glucose levels without changes in serum insulin levels suggests a glucose intolerance state, as it was also seen in our previous hypoxia studies." (PMID 37656229, 2023). "HFat diet led to a more profound impact on hepatic glucose and lipid metabolism than HFruct, with mice presenting glucose intolerance, increased saturated fatty acids, and no glycogen pool, yet both HFat and HFruct presented hepatic insulin resistance." (PMID 36060961, 2022). "Additionally, we determined that systemic administration of FPP improved glucose intolerance in HFD-induced obese WT mice, an effect that is mediated through stimulation of insulin secretion." (PMID 36066975, 2022). "The TrspRIPKO mice gained more excess weight, while on an HFD, compared to Trsp floxed control mice lacking Cre recombinase, and displayed glucose intolerance, hypothalamic leptin resistance, and systemic insulin resistance." (PMID 36499772, 2022). "Strikingly, mouse lemurs are protected against glucose intolerance during fattening, but not during the second half of winter when they lose fat and exhibit increased fasting insulin levels." (PMID 35457071, 2022). "Assessment of insulin sensitivity revealed that chow-fed 11β-HSD1 KO mice were not protected from the development of glucose intolerance, hyperinsulinaemia, or a worsening HOMA-IR index with age." (PMID 36205523, 2022). "Consistently, in response to bolus of glucose treatment, βOGAKO mice failed to significantly increase insulin secretion, compared to control mice, suggesting insulin secretion deficit as the driver of glucose intolerance at this age." (PMID 36387851, 2022). "Resting glucose was not correlated with body mass, while glucose intolerance and serum insulin levels both displayed a significant linear correlation." (PMID 36424602, 2022). "Previously, we reported that acute HFHS exposure did not result in glucose intolerance or altered serum insulin levels at day 0 of pregnancy." (PMID 36520818, 2022). "They reported that at 18 weeks old, the p66Shc-negative lean mice showed more glucose intolerance, and also at age of 30 weeks, they showed worse insulin sensitivity." (PMID 36465704, 2022). "In individuals with nondiabetic glucose intolerance, fasting glucose and insulin concentrations are highly correlated positively." (PMID 36613602, 2022). "The study participants were ten healthy subjects with no glucose intolerance (normal subjects) (mean, 24.4 ± 4.8 years) and nine subjects with impaired glucose tolerance (mean, 45.2 ± 11.1 years, including 2 on insulin therapy)." (PMID 35742001, 2022). "ATG5 might play a crucial role in the production and secretion of insulin in pancreatic β cells, and deletion of ATG5 results impaired insulin secretion and glucose intolerance." (PMID 36313818, 2022). "The F1 offspring derived from the microinjection of HFD caudal sperm RNA ranging from 30 to 40 nt to normal zygote mimicked the glucose intolerance in F1 offspring derived from whole-sperm head injection, but not the insulin sensitivity." (PMID 36555356, 2022).
Glucose intolerance (continued). "In contrast, male C57BL/6J mice exposed to 50 ppm of sodium arsenite for 8 weeks developed glucose intolerance without impairment in insulin sensitivity." (PMID 35651975, 2022). "Interestingly, age matters, as 4 weeks of HFD increased plasma glucose and insulin levels in 12-month-old male Tg APP/PS1 mice, while mice of 6 months of age had similar blood glucose levels compared to WT mice, in parallel with glucose intolerance." (PMID 35958733, 2022). "Body weight did not change for the duration of the metabolic challenge, but glucose intolerance worsened, with insulin secretion deficit, compared to mice fed normal chow diet." (PMID 36387851, 2022). "Altered OGTT but normal ITT suggests that while animals had impaired glucose tolerance (glucose intolerance), their insulin responsiveness was not affected." (PMID 36714129, 2022). "GPR84−/− mice on MCFA-enriched diet exhibit glucose intolerance and a defect in insulin secretion, which was not reproduced in a different study." (PMID 34943862, 2021). "In addition, HFD plus NaCl-fed mice showed lower plasma insulin levels than HFD-fed mice and glucose intolerance during a GTT." (PMID 33730054, 2021). "Circulating insulin levels were reduced in both Mrps12ep/ep and Mrps12ha/ha mice on both diets when compared to control mice, however, the reduction in circulating insulin levels was greater in the Mrps12ep/ep mice fed on an HFD, consistent with their glucose intolerance." (PMID 34096683, 2021). "Glucose intolerance in CHOW+SE-HFD mice may be due to insulin insufficiency, rather than insulin resistance in CHOW+SHAM-HFD, as reflected by plasma insulin levels in these two groups." (PMID 33796546, 2021). "Lamming and others went on to show that rapamycin also disrupts mTORC2 in multiple tissues, leading to insulin insensitivity and glucose intolerance, and this mTORC2 disruption has negative effects on lifespan." (PMID 35251892, 2021). "In contrast, the TSC2-KOPlacenta mice appear to have increased insulin sensitivity without glucose intolerance." (PMID 34032632, 2021). "We show that GIP receptor KO mice exhibit glucose intolerance in the presence of impaired insulin response after 100 and 125 mg glucose, but not after lower doses of glucose." (PMID 34122340, 2021). "In our study, the insulin sensitivity was comparable between SIRT2-KO and WT rats, but blood insulin level after glucose loading was markedly decreased in SIRT2-KO rats, which may explain glucose intolerance." (PMID 33754030, 2021). "Cumulatively, these data suggest that there may be a defect in both insulin granule movement and exocytosis in α-syn knockout animals, leading to the reduction in GSIS and glucose intolerance observed in these mice." (PMID 34393754, 2021). "Adult Jamaican survivors of childhood marasmus, compared with never malnourished controls, had more glucose intolerance, lower insulin secretion, and reduced insulin sensitivity." (PMID 33740034, 2021). "In conclusion, our study findings reveal that muscle TGR5 improves glucose intolerance induced by HFD or aging without affecting muscle insulin sensitivity." (PMID 33262218, 2021). "In conclusion, continuous exposure to high-intensity infrasound increases corticosterone levels, without inducing glucose intolerance and alteration of plasma insulin or peripheral insulin sensitivity through GLUT4 transporter." (PMID 34446814, 2021). "HFD+SE-HFD offspring developed more severe glucose intolerance during IPGTT than CHOW+SHAM-HFD and CHOW+SE-HFD offspring (p < 0.05); however, only CHOW+SHAM-HFD and HFD+SE-HFD offspring showed increased plasma insulin levels." (PMID 33796546, 2021). "However, AclyM-KO mice displayed slightly aggravated glucose intolerance after HFD feeding, whereas insulin sensitivity was unaffected." (PMID 33981315, 2021). "Compared to tamoxifen-treated littermate controls, Tg(βmiR-21) mice exhibited mild glucose intolerance on IPGTTs, without significant differences in insulin tolerance." (PMID 34246804, 2021).
Glucose intolerance (continued). "This delay in insulin level changes and GLUT4 activation might be the important reasons for glucose intolerance of this fish species." (PMID 33178047, 2020). "In a high-fat-fed mouse model, MT at a dose of 100 mg/kg/day for 28 days, reduced glucose intolerance and plasma insulin levels, hepatic triglyceride levels, and obesity, without affecting caloric intake." (PMID 33041782, 2020). "Activation of TLR4 induces liver injury and fibrosis by triggering the production of various pro-inflammatory cytokines; mice lacking hepatocyte TLR4 exhibit improved glucose intolerance, insulin sensitivity, and hepatic steatosis." (PMID 32182914, 2020). "HF diet resulted in expected metabolic alterations across groups (increased body and fat mass; glucose intolerance; increased plasma insulin and leptin, decreased ghrelin; nonalcoholic fatty liver disease-related pathology)." (PMID 32993686, 2020). "Lack of Ogn expression increases glucose intolerance and elevates insulin levels in HFD-fed Ogn–/– mice and ectopic administration of OGN improves glucose tolerance." (PMID 32508807, 2020). "Nitrate/nitrite treatment also improved glucose intolerance in eNOS−/− mice, reduced fasting blood glucose in db/db mice, rescued glucose intolerance and HOMA-IR in diabetic KKAy mice, and reversed insulin levels with improvement in GTT and PTT in HFD fed diabetic rats." (PMID 32806494, 2020). "In mice submitted to a typical American “fast food” diet, NDGA normalized insulin sensitivity, but not glucose intolerance, body and fat pad weight, ALT, AST, and liver triglycerides." (PMID 32184727, 2020). "Mice genetically lacking adipsin had glucose intolerance due to fasting and glucose-stimulated insulinopenia, while isolated islets from these mice had reduced glucose-stimulated insulin secretion." (PMID 33233515, 2020). "Note that the applied procedure did not induce any glucose intolerance as documented by the time courses of insulin release after glucose injection and concomitantly performed glucose tolerance tests." (PMID 32664368, 2020). "Elevation of low-grade inflammation might have interfered with insulin signaling and regulation of plasma glucose levels in women with GDM, leading to glucose intolerance." (PMID 32500037, 2020). "This glucose intolerance was due to a reduced insulin response to glucose as opposed to any effect on insulin sensitivity." (PMID 31619585, 2019). "Intriguingly, PIN1 augments the uptake of triglycerides and fosters differentiation of MEFs into adipose cells in response to insulin, whereas PIN1KO mice are insulin resistant, have glucose intolerance and display lower adipose tissue weight when fed with high fat diet." (PMID 30873382, 2019). "In mice fed HFD, body weight, blood glucose and plasma insulin levels are higher, and glucose intolerance is apparent, but insulin sensitivity evaluated by ITT is not decreased, compared to that in mice fed NC within 1 week of intervention of the diets." (PMID 31083314, 2019). "Consistent with this milder phenotype, age-matched female littermates showed only partial glucose intolerance as compared to males and did not become insulin-resistant upon HFD feeding." (PMID 31752326, 2019). "At PW24, the basal levels of serum glucose and insulin were not changed, however, weakened glucose intolerance and enhanced insulin sensitivity were found in the PEE male offspring." (PMID 30778335, 2019). "Thenumber of patients included and the method we used to assess glucose intolerance(HOMA alone, glucose and fasting insulin) may have influenced the outcome." (PMID 30328467, 2019).
Glucose intolerance (continued). "Moreover, purified SeP treatment significantly impaired insulin-mediated AKT phosphorylation in hepatocytes and systemic insulin sensitivity, whereas knockdown of SeP in the liver improved glucose intolerance." (PMID 31405033, 2019). "On the contrary, animals exposed to the highest dose showed mild glucose intolerance with no changes on insulin sensitivity." (PMID 30429829, 2018). "The interruption of insulin or glucose signaling in POMC neurons leads to glucose intolerance without changing energy homeostasis." (PMID 30283405, 2018). "There is a close relationship between insulin sensitivity and testosterone concentrations in men across a wide range of glucose intolerance, including those with T2DM, and independent of SHBG concentrations." (PMID 29566712, 2018). "Both male and female Adrb2 cKO mice showed normal insulin sensitivity, suggesting that the glucose intolerance in female Adrb2 cKO mice does not stem from defects in insulin responsiveness." (PMID 30303066, 2018). "Altogether, these results suggest that POMC prevents glucose intolerance by improving insulin sensitivity through mechanisms not related to energy balance regulation or fat storage." (PMID 30283405, 2018). "However, HFD fed animals presented liver fat accumulation, postprandial glucose intolerance, white adipose tissue (WAT) insulin resistance, and inflammation." (PMID 30510205, 2018). "Strikingly, in aged mice, but not in young mice, we discovered that WD-induced glucose intolerance and weight gain is highly correlated with the hypersecretion of insulin." (PMID 30546031, 2018). "In well-designed laboratory experiments, intermittent hypoxia and fragmented sleep resulted in increased insulin resistance without an adequate compensatory insulin response, leading to glucose intolerance." (PMID 29707586, 2018). "Raised fasting and post-stimulus glucose levels (≥100 and ≥140 mg/dL, respectively) are indicators of an advanced metabolic impairment (glucose intolerance) in which insulin can no longer maintain blood glucose levels in the normal range." (PMID 29082896, 2018). "Liver-ChREBP KO mice displayed glucose intolerance, which was most likely due to insulin no longer being able to suppress hepatic glucose production (HGP) effectively." (PMID 29107286, 2017). "Supporting this notion, mice lacking both the insulin and leptin receptors on POMC neurons do not suppress HGP normally, an effect associated with systemic glucose intolerance and insulin resistance." (PMID 28469281, 2017). "HG mice also had glucose intolerance and elevated insulin levels, but not as drastic, with a p value < 0.05 (HG vs STD), instead of < 0.001." (PMID 29180700, 2017). "Low dose aspartame consumption in drinking water has been shown to increase fasting blood glucose levels and induce glucose intolerance without an effect on fasting plasma insulin levels in both rats and mice." (PMID 28489050, 2017). "After an overnight fast, the KO mice had higher insulin levels compared to their wild type littermates which was not due to due to glucose intolerance." (PMID 28768896, 2017). "The LAN-induced glucose intolerance at the start of the dark period was reflected by increased plasma glucose levels, whereas LAN-induced glucose intolerance at the end of the dark period was mainly reflected by increased plasma insulin." (PMID 28374068, 2017). "HFD fed rats did not present glucose intolerance, however, these animals showed a great increase in insulin secretion after glucose stimulus, indicating that these animals present lower insulin sensitivity." (PMID 29220408, 2017). "Additionally, both SR141716A and TXX-522 dramatically decreased the fasting blood glucose and insulin levels, but oral glucose tolerance testing showed that TXX-522 (5 mg/kg) ameliorated glucose intolerance more than the same dose of SR141716A did." (PMID 29051736, 2017).
Glucose intolerance (continued). "In contrast to a high fat diet feeding, pregnancy did not result in a clear glucose intolerance, while glucose stimulated insulin release per islet was significantly increased at P15.5 and also insulin content per islet was increased." (PMID 28792951, 2017). "In effect, pre-meal moderate-intensity exercise exacerbates evening glucose intolerance regardless of the dietary composition of the meals and without an effect on the dietary influence over evening postprandial insulin, GIP, and HOMA-IR." (PMID 27798656, 2016). "Treatment by DPP4i failed to improve glucose intolerance and insulin secretory response in mSTZ-control mice during IPGTT and OGTT." (PMID 27053237, 2016). "This in turn would decrease plasma insulin levels without altering insulin sensitivity and hence inducing glucose intolerance." (PMID 26563389, 2016). "Mice fed with HFD showed augment of body weight gain, weights of adipose depots, fasting insulin levels, HOMA-IR, constant of glucose disapearance (Kitt), the area under the curve (AUC) of GTT, and so IR and glucose intolerance conditions were established already after 4 weeks." (PMID 27445979, 2016). "Furthermore, the mice treated with nutlin-3a exhibited severe glucose intolerance and defective GSIS, but normal insulin sensitivity as determined by ITT." (PMID 27265727, 2016). "Treatment with DPP4i potentiated glucose-induced insulin secretion and ameliorated glucose intolerance in mSTZ-GcgKO but not in mSTZ-DKO mice." (PMID 27053237, 2016). "The measured glucose intolerance, elevated fasting insulin levels, and elevated non-fasting blood glucose levels implied a defect in skeletal muscle glucose uptake." (PMID 27486508, 2016). "Although GcgKO mice lack GLP-1, treatment with DPP4i potentiated glucose-induced insulin secretion and ameliorated glucose intolerance in mSTZ-treated GcgKO mice, but did not increase beta cell area or significantly reduce apoptotic cells in islets." (PMID 27053237, 2016). "Mice lacking hepatic Lkb1 had glucose intolerance after injection of glucose, and normal reduction in blood glucose in response to insulin injection." (PMID 27824128, 2016). "As glucose tolerance is influenced by both peripheral insulin sensitivity and blood insulin concentration, modest IR does not necessarily result in glucose intolerance if insulin levels increase accordingly." (PMID 26662513, 2016). "Agonist treatments that did not increase body temperature (KB2115 and the lowest dose of GC-1) produced the most pronounced glucose intolerance and failed to improve insulin sensitivity." (PMID 25849936, 2015). "Ten weeks of EE (and exercise) improved HFD-induced fasting serum glucose levels and glucose intolerance in GTTs, but did not improve serum insulin levels during fasting or 60 m after i.p. glucose injection, compared to APP-HFD mice in standard housing." (PMID 26340637, 2015). "TIMP-1 deficient mice were protected from HFD- and IFSD-induced development of hepatic steatosis and glucose intolerance, but TIMP-1 deficiency did not change peripheral insulin sensitivity or insulin secretion." (PMID 26168159, 2015). "We have previously shown in our population that 39.1 % of women with a recent history of GDM, had glucose intolerance based on the OGTT three months postpartum and that these women also had a persistent impaired beta-cell function and lower insulin sensitivity postpartum." (PMID 26497130, 2015). "In contrast, fa/fa rats in the nondiabetic ZF strain maintain mild glucose intolerance by increasing insulin secretion with age." (PMID 25961052, 2015). "Similarly, Par14 enhances insulin-induced IRS-1 tyrosine phosphorylation, and Par14 knockdown exacerbated the glucose intolerance in Pin1 knockout mice." (PMID 26074875, 2015). "This indicates that STZ-induced glucose intolerance and insulin insensitivity were not changed by sham surgery or time." (PMID 26185767, 2015).